MIR548K (microRNA 548k)
Synonyms: hsa-mir-548k; MIRN548K
Gene: MicroRNA gene on chromosome 11 (70,283,955 to 70,284,070, forward strand). Ensembl gene ENSG00000221333.
Homologues: Orthologues: chimpanzee ptr-mir-548k (100% identical). Paralogues in human: MIR548AA1 (66% identical), MIR548H3 (66% identical), MIR548AZ (65% identical), MIR548Z (59% identical), MIR548X2 (58% identical), MIR548AY (57% identical), MIR548AN (55% identical), MIR548F3 (55% identical), MIR548F1 (54% identical), MIR548N (54% identical), MIR548P (53% identical), MIR548X (52% identical), and 13 more.
Diseases named in the same sentence as MIR548K in open-access papers:
MIR548K is named in the same sentence as 2 diseases in open-access papers, as found by Europe PMC text mining. Sharing a sentence is not in itself a finding about the gene and the disease. The quoted sentences say what the papers report.
esophageal squamous cell carcinoma (1 paper, 2016). Esophageal squamous cell carcinoma (ESCC) is a type of esophageal carcinoma (EC) that can affect any part of the esophagus, but is usually located in the upper or middle third. "This region includes MIR548K, a microRNA recently characterized as a novel oncogene in esophageal squamous cell carcinomas (ESCC), a tumor entity that shares common risk factors and genomic alterations with HNSCC." (PMID 27027432, 2016).
MIR548K also shares sentences with these, for which no sentence is quoted: tumor (1 paper).